NLRP3 (NLR family pyrin domain containing 3)
Diseases named in the same sentence as NLRP3 in open-access papers (continued):
Sharing a sentence is not in itself a finding about the gene and the disease.
tumor (continued). "Inflammasome-forming NLRs have been found to significantly regulate the tumor microenvironment by modulating cytokine production, and the TCGA database and our patient cohort showed reduced NLRP3 expression." (PMID 26378020, 2015). "We found that IL12 (isoforms A and B) and NLRP3 were upregulated in 97L/STC1-derived tumor xenografts." (PMID 26469082, 2015). "The NLRP3 inflammasome functions as a positive regulator of tumor cells proliferation and metastasis." (PMID 24587153, 2014). "Allograft tumor growth was slower in Il17a−/−, Il1r1−/−, Nlrp3−/−, and Casp1−/− mice after chemotherapy treatment, demonstrating all elements in this pathway play a part in tumor protection although the exact mechanism is unclear." (PMID 24795727, 2014). "The CD11b+Gr-1int myeloid cells secreted CCL5 and CXCL9 that were important for recruiting NK cells into the tumor microenvironment, demonstrating a role for NLRP3 in the suppression of NK cell activation and promotion of a suppressive tumor environment." (PMID 24273542, 2013). "The decrease in tumor formation was attributed to an increase in natural killer (NK) cells and CD11b+Gr-1int myeloid cells seen in Nlrp3−/− mice." (PMID 24273542, 2013). "Nlrp3−/− mice treated with methylcholanthrene (MCA) exhibited prolonged tumor-free survival compared to wild-type mice." (PMID 24273542, 2013). "It should be noted that in another study utilizing the AOM-DSS model, Nlrp3−/− mice exhibited a similar tumor load as WT mice." (PMID 24273542, 2013). "Taken together these findings demonstrate a role for NLRP3 activation in skewing a Th17 response and leading to a decreased anti-tumor response." (PMID 24273542, 2013). "In contrast, the chemotherapeutic agents gemcitabine (Gem) and 5-fluorouracil (5FU), which have been shown to deplete myeloid derived suppressor cells (MDSCs), activated NLRP3 in MDSCs resulting in a diminished anti-tumor response." (PMID 24273542, 2013). "The ability of NP’s components to directly influence NLRP3 inflammasome is very important since it has been described that NLRP3 inflammasome and subsequent IL-1β secretion is critical for stimulation of anti-tumor T cells responses following chemotherapy." (PMID 23087900, 2012). "In tumour cells, AIM2 and RIG-I are required for IL-1β induction by EBV genomic DNA and EBV-encoded small RNAs, respectively, while NLRP3 responds to extracellular ATP and reactive oxygen species." (PMID 23065753, 2012). "Collectively, these findings indicate that AIM2, RIG-I and NLRP3 inflammasomes in tumour cells are activated by factors from the viral and tumour microenvironments, thus contributing to IL-1β secretion." (PMID 23065753, 2012). "NLRP1 and NLRP3 inflammasomes are promising tumour markers for NMSC." (PMID 42222687, 2026). "For instance, tumor-resident bacteria such as Fusobacterium nucleatum and Escherichia coli have been shown to promote colorectal carcinoma via modulation of immune pathways (e.g., NLRP3 inflammasome), thereby shaping the tumor TME toward immunosuppression and metastasis." (PMID 41560793, 2026). "This literature review shall further examine and summarize whether NLRP1 and NLRP3 inflammasomes could be potential tumour markers of NMSC." (PMID 42222687, 2026). "Besides, NLRP3 has been implicated in promoting tumor metastasis, indicating the critical role of NLRP3 inflammasome in tumor progression." (PMID 40135589, 2025). "In vivo studies could involve xenograft models treated with NLRP3 inhibitors and metabolic modulators, with analysis of tumor growth, metabolic shifts, and treatment response." (PMID 40718836, 2025). "NLRP3, a member of inflammasome, has been noticed a tumor promotion role." (PMID 40135589, 2025). "In this study, we aimed to test the effects of MCC950, a specific NLRP3 inhibitor, on the prevention of vincristine‐induced adverse effects as well as tumor progression and vincristine efficacy in NOD/SCID/interleukin‐2 receptor γ‐negative mice patient‐derived xenografts of ALL." (PMID 40104043, 2025).
tumor (continued). "Activation of caspase-11 and caspase-4 not only directly contributes to NLRP3 activation but may also influence the dynamics of the tumor immune microenvironment, thereby promoting immune evasion in tumors." (PMID 40718836, 2025). "Conversely, in CRC liver metastases, HNSCC, and NPC, NLRP3 plays a significant role in promoting immune surveillance, boosting NK cytotoxicity, reshaping the anti-tumor response, and preventing local relapse through IL-1β-driven recruitment of anti-tumor neutrophils." (PMID 40155968, 2025). "Similarly, tumor size on Day 49 in the NLRP3/α-PD-1 + α-CTLA-4 group was significantly smaller compared to the NLRP3 agonist alone or the ICIs alone group (p = 0.009 and 0.029, respectively)." (PMID 39871312, 2025). "Therefore, exploring the regulatory interactions between NLRP3 and the S6K1-GLI1 pathway in CRC can help elucidate the contributions of NLRP3 to the tumor development process." (PMID 39744485, 2025). "These pathways not only support the rapid proliferation and growth of tumor cells but may also offer new insights into the dual role of NLRP3 inflammasome in cancer." (PMID 40718836, 2025). "However, a series of studies elucidated the involvement of NLRP3, a key gene related to cuproptosis, in interactions with intestinal flora, highlighting its role in tumor development." (PMID 40520902, 2025). "Elevated NLRP3 levels in the poor prognosis group may reflect a more aggressive tumor phenotype characterized by enhanced inflammation and immune evasion." (PMID 41479846, 2025). "Specifically, studies have shown that in cancer cells undergoing Snail-induced epithelial–mesenchymal transition (EMT), tumor cells can deliver miR-21 via exosomes to inhibit the activity of the NLRP3 inflammasome in TAMs, thereby enhancing the resistance of tumor cells." (PMID 40304000, 2025). "However, NLRP3 inflammasome is activated by a tumor-derived signal in the immune cells that cleaves pro-IL-1β to active IL-1β by caspase-1 and finally promotes thrombosis in the IL-1β/NLRP3 pathway." (PMID 39857281, 2025). "Furthermore, a significant difference in NLRP3 expression was observed in tumor cells exposed to the two PTX-containing scaffolds, the most suitable for PTX delivery being GFAP (p < 0.05)." (PMID 39940603, 2025). "Furthermore, although new-generation inhibitors demonstrate greater specificity for the NLRP3 complex, they still lack tumor-selective activity, raising concerns about off-target effects in tissues with physiological inflammasome functions." (PMID 41560727, 2025). "So far, tumor-derived or chemotherapy-induced ICD with an ensuing release of alarmins is able to activate the NLRP3 inflammasome due to the alteration of the mitochondrial homeostasis or the AIM2 inflammasome after the recognition of double-stranded DNA (dsDNA) released by dying cells." (PMID 39857785, 2025). "Additionally, the ERS-pyroptosis axis is closely associated with metabolic reprogramming, such as glucose metabolism disorders and TXNIP/NLRP3 pathway activation, influencing tumor progression." (PMID 41407677, 2025). "In skin and bone metastases, NLRP3 suppresses NK and T cell responses, favoring tumor progression." (PMID 40155968, 2025). "Therefore, we chose the ALL‐19 PDX model to assess the effect of NLRP3 inhibition on tumor progression and vincristine monotherapy efficacy." (PMID 40104043, 2025). "Moreover, inflammatory signaling pathways, including NF-κB, JAK-STAT, and NLRP3, are aberrantly activated within the tumor microenvironment, further driving tumor cell proliferation, invasion, and the development of therapeutic resistance." (PMID 40881678, 2025). "Elevated levels of 3HB are associated with tumor invasiveness, with its ability to modulate gene expression through histone deacetylase (HDAC) inhibition and suppression of the NLRP3 inflammasome, one of the few mechanisms that can suppress CRC metastatic growth." (PMID 39941796, 2025).
tumor (continued). "Meanwhile, pyroptosis induced by the NLRP3 inflammasome can inhibit tumor progression." (PMID 40718836, 2025). "Additionally, multiplex immunofluorescence staining revealed co-localization of TMEM71 with NLRP3 in NPC tumor cells." (PMID 39951856, 2025). "Therefore, we make the TLR4/NF-κB/NLRP3 inflammasome as the main line, supplemented by serum inflammatory factors, peripheral blood cell typing, tumor cell proliferation and apoptosis indicators to explore the anti-EC effect of Ori in this study." (PMID 40606986, 2025). "Impaired mitophagy can lead to mitochondrial dysfunction and ROS accumulation, while abnormal activation of the NLR pathway, particularly via the NLRP3 inflammasome, promotes chronic inflammation and immune evasion, influencing ferroptosis and the tumor microenvironment." (PMID 40959429, 2025). "Moreover, the therapeutic promise of targeting the NLRP3 inflammasome also extends to oncology; studies show that, depending on the tumour environment, altering this pathway can either promote or hinder the proliferation of cancer cells." (PMID 40205269, 2025). "In conclusion, these findings suggest a pro‐tumor role for NLRP3 in cancer." (PMID 40671401, 2025). "Moreover, the highly enriched P. gingivalis in tumor tissues can activate the NLRP3 inflammasome and induce neutrophils to release elastase, thereby fostering inflammatory responses and shaping the suppression of the tumor immune microenvironment." (PMID 39966840, 2025). "In a similar vein, miR‐495 alleviates chronic inflammation in the tumor's local environment by targeting both NLRP3 and caspase‐1, suggesting that miRNAs may have a broader ability to reduce inflammation that would otherwise foster tumor growth." (PMID 40671967, 2025). "Furthermore, 8 decreased NLRP3 inflammasome activation, as shown by reduced NLRP3 and caspase-1 p20 expression in tumor tissues treated with 8 and 5-FU." (PMID 40422787, 2025). "Multi-omics data integration could help identify novel metabolic pathways regulated by NLRP3 that contribute to tumor progression." (PMID 40718836, 2025). "The NLRP3 inflammasome may primarily influence tumor immunity by mediating the actions of tumor‐infiltrating lymphocytes and macrophages." (PMID 40671401, 2025). "On the other hand, the NLRP3 inflammasome may inhibit tumor progression by modulating immune responses and inducing pyroptosis in cancer cells." (PMID 40718836, 2025). "Also, resibufogenin 62 exerts its pyroptotic activity on NSCLC tumor cells by activation of caspase-1/NLRP3." (PMID 39316325, 2025). "Loss of NLRP3 disrupted this process, leading to heightened Th17 inflammatory output (IFN-γ, Granzyme B, TNF-α) and restored CD8+ T-cell cytotoxicity, ultimately constraining tumor growth." (PMID 41291696, 2025). "Notably, the dual role of NLRP3 appears to be closely related to the composition and activation state of immune cells within the tumor microenvironment (TME)." (PMID 40718836, 2025). "The lack of significant differences in tumor growth between fully Nlrp3-deficient mice and CD4Nlrp3fl/fl mice that we observed suggests a predominant role of NLRP3 in CD4+ T cells during tumor progression." (PMID 40195474, 2025). "Interestingly, the results showed that the chemo > STING/α-PD-1 + α-CTLA-4 treatment had significantly better tumor growth suppression than chemo > NLRP3/α-PD-1 + α-CTLA-4." (PMID 39871312, 2025). "(2021), showed that radiation-induced NLRP3 inflammasome activation promotes anti-tumor immunity." (PMID 40692785, 2025). "NLRP3 inflammasome activation in tumor microenvironment can promote the infiltration of cytotoxic lymphocytes and antitumor immunity, but it is unclear whether ICB resistance can be overcome by directly targeting NLRP3." (PMID 40185713, 2025).
tumor (continued). "These sections also had distinct expression of NLRP3 protein in cytoplasm of tumor cells." (PMID 41410801, 2025). "NLRP3 plays a key role in cellular pyroptosis and tumor progression." (PMID 39951856, 2025). "As a result, NLRP3 pathway has complicated consequences on tumor initiation and development." (PMID 41560727, 2025). "The crosstalk between EMT and the inflammasome is an overlooked mechanism of tumour evolution, and targeting inflammasomes like NLRP3, or their downstream signalling pathways, offers a promising therapeutic avenue, with the objective of inhibiting metastasis and overcoming drug resistance." (PMID 41148809, 2025). "Given the emerging role of NLRP3 in a variety of cancers, NLRP3 inflammasome is emerging as a research topic of interest in the field of the tumor microenvironment, and the potential for their development as important biomarkers for cancer diagnosis or prognosis is quite high." (PMID 40671401, 2025). "Interestingly, a specific population of CD146 + macrophages within the TME has been found to enhance anti-tumor immunity through NLRP3 inflammasome activation." (PMID 40155968, 2025). "The correlation analysis of immune cell infiltration showed that CASP1, NLRP3, and AIM2, which showed that pyroptosis was involved in the infiltration of immune cells in the tumor microenvironment and NLRP1 exhibited high diagnostic efficacy, while PYCARD demonstrated poor diagnostic efficacy." (PMID 40026444, 2025). "NLRP3 levels and downstream effectors, like caspase-1 and IL-1β, can be measured as direct biomarkers and surrogate biomarkers by immunohistochemistry, qRT-PCR in tumor tissues of biofluids." (PMID 41560727, 2025). "Finally, exosomal cargo can modulate the NOD-, LRR-, and pyrin domain-containing protein 3 (NLRP3) inflammasome, activating pro-inflammatory responses that influence tumor development and immunomodulation." (PMID 40443670, 2025). "To investigate how Nlrp3 deficiency affects the chitosan-stimulated tumor microenvironment (TME), we further analyze the percentages of immune cell populations in Nlrp3-/- mice compared with their WT counterparts, particularly neutrophils and monocytes responsible for IL-1β inflammation." (PMID 40860135, 2025). "NLRP3 activation may improve anti-tumour immunity in malignancies with low levels of IL-1β production, while NLRP3 inhibition may help stop tumour growth in tumours with high amounts of IL-1β." (PMID 40205269, 2025). "In immunosuppressive conditions, excessive expression of IL-1β downstream of NLRP3 activation may promote tumor progression by exacerbating chronic inflammation and facilitating immune evasion." (PMID 40718836, 2025). "Consequently, the significance of pyroptosis and its associated genes (such as CASP1, GSDMD, NDO1, NOD2, NLRP3, NLRP6 and so on) in tumor therapy has gained significant attention." (PMID 40520902, 2025). "In addition, NLRP3 activation in neutrophils induces IL-1β and IL-18 secretion, promotes chronic inflammation and enhances tumor growth." (PMID 41157253, 2025). "Similarly, simvastatin 64 exerts its pyroptotic activity on tumor cells by activation of caspase-1/NLRP3 pathway." (PMID 39316325, 2025). "NLRP3 is a multiprotein complex that regulates macrophages, promoting secretion of pro-inflammatory cytokines such IL-18 and IL-1β by macrophages and this in turn was shown to optimize anti-tumor activity of NK cells and restrict tumor growth." (PMID 38533720, 2024). "Therefore, inhibiting NLRP3 has been suggested to suppress tumor aggression by reducing the release of inflammatory cytokines." (PMID 38543085, 2024). "Furthermore, interference with platelet NLRP3 signal transduction significantly improves the survival rate of tumor mice." (PMID 38182564, 2024). "In addition, the inflammatory response triggered by the NLRP3 inflammasome can also stimulate anti-tumor immunity, which enhances the T-cell-mediated elimination of cancer cells." (PMID 39769450, 2024).
tumor (continued). "In this clinical cohort, we also found that the p-NF-κB p65 and NLRP3 protein levels and M1 macrophage infiltration were increased in the tumor tissues of patients who responded to immunotherapy, while they were reduced in those who did not respond to immunotherapy." (PMID 38062129, 2024). "Recent research suggests that NLRP3 plays an essential role in tumor development; therefore, intensive study of its mechanism is warranted as it could play a key role in the treatment of digestive system tumors." (PMID 38182564, 2024). "The results showed that the depletion of NLRP3 significantly promoted tumor growth." (PMID 38697992, 2024). "Activation of the NLRP3 inflammasome can have both oncogenic and tumor-suppressive effects in HCC." (PMID 39544286, 2024). "The main reason may lie in the ability of ROS to activate the NLRP3 inflammasome, promoting the invasion and migration of tumor cells." (PMID 39011036, 2024). "In addition, NLRP3, as an important inflammasome, is involved in immune checkpoint-related tumor immunotherapy." (PMID 38575922, 2024). "On one hand, NLRP3 inflammasome could act as a driver of tumor progression through chronic inflammation." (PMID 39769450, 2024). "Notably, the mutation frequencies of key ICDRGs, such as PI3KA, NLRP3, CASP8, and TLR4, highlight the potential role of genetic alterations in modulating immune responses within the tumor microenvironment." (PMID 39372411, 2024). "This may suggest that the NLRP3 inflammasome pathway is active and that pyroptosis occurs within OC cells but the effect of the NLRP3 on clinical tumour initiation or progression cannot be determined by this type of analysis alone." (PMID 39516433, 2024). "NLRP3 participates in physiological and pathological processes, including tumour progression." (PMID 38103146, 2024). "However, it should be noted that the significance of NLRP3 as a potential marker in tumor therapy cannot be overlooked." (PMID 39201564, 2024). "Similarly, in B16F10 melanoma, the inhibition of NLRP3 reduced tumor growth and synergized with checkpoint blockade therapy, suggesting that inflammasome-derived IL-1β promotes tumorigenesis." (PMID 38391959, 2024). "However, NLRP3 promotes the immune infiltration of tumours and is closely related to immune escape by regulating IC." (PMID 39318060, 2024). "Thus, NLRP3 inflammasome manipulation in combination with anti-tumor drugs opens up new therapeutic perspectives for TNBC therapy." (PMID 39433537, 2024). "More recently, it was revealed that the NLRP3 inflammasome also regulates tumor progression." (PMID 39230586, 2024). "However, previous studies have shown that the priming signal of NLRP3 can be provided by tumor-produced IL-1." (PMID 38543085, 2024). "Conversely, deficiencies in the NLRP3 inflammasome have shown a potential to increase tumor burden in certain cancers, such as colitis-associated cancer, due to a lack of tumor-suppressing cytokines." (PMID 39769450, 2024). "At the same time, opposing views argue that NLRP3-dependent death may increase tumor growth because it increases the release of proinflammatory cytokines." (PMID 38543085, 2024). "Bronchopulmonary cancer develops in inflammatory tumor microenvironment, which may involve the NLRP3 pathways." (PMID 39882243, 2024). "Reports have shown that NLRP3 inflammasomes are necessary for anti-tumor effect during radiation." (PMID 39318624, 2024). "In summary, the results of this study suggest that XLOC_000647 not only acts as a new tumor-inhibiting factor of lncRNA, but also may be regarded as a major adjustment factor of NLRP3, which is able to inhibit cell proliferation, invasion, and EMT of PDA." (PMID 38182564, 2024). "The role of the NLRP3 inflammasome varies according to sex, age, and tumor type." (PMID 38649928, 2024).